ALDH2 (aldehyde dehydrogenase 2 family member)
Diseases named in the same sentence as ALDH2 in open-access papers (continued):
Sharing a sentence is not in itself a finding about the gene and the disease.
Hypertension (continued). "Several cross-sectional studies and case–control association studies have consistently reported significant association between ALDH2 genetic polymorphisms and blood pressure and hypertension in East Asian population." (PMID 22839215, 2012). "In summary, we demonstrated that ALDH2 genetic polymorphism predicted development of hypertension in a prospective cohort." (PMID 22839215, 2012). "In this study, we demonstrated that a common ALDH2 genetic polymorphism was associated with progression to hypertension in a prospective Chinese cohort." (PMID 22839215, 2012). "Additionally, the rs671 marker in the ALDH2 gene was associated with reduced prevalence of hypertension risk in individuals with a low METS-IR." (PMID 39684400, 2024). "Since low serum LDLc levels might increase the risk of hypertension by reducing angiogenesis activity, BRAP rs3782886, which has a strong LD with ALDH2 rs671, might have a beneficial influence on reducing the risk of hypertension by activating platelets." (PMID 37511963, 2023). "In this study, ALDH2 rs671 G/A, A/A genotypes may be risk factors for hypertension in a Chinese Hakka population." (PMID 35346052, 2022). "ALDH2, which is associated with a poorer functional outcome of ischemic stroke and increases the risk and susceptibility to hypertension or diabetes, has been found to protect against stroke by clearing the toxic aldehydes, for example, 4-hydroxy-2-nonenal (4-HNE)." (PMID 35449099, 2022). "Our study also demonstrated that ALDH2*2 is associated with a lower incidence of hypertension, which may be linked to lifestyle behaviors, including alcohol intake, eating habits, mental stress and so on." (PMID 36426220, 2022). "There were some studies on the relationship between ALDH2 gene polymorphisms and hypertension." (PMID 35346052, 2022). "Moreover, it has already been reported that the GG genotype of rs671 of ALDH2 is associated with an increased risk of hypertension, especially in men." (PMID 34828409, 2021). "SNPs in ALDH2 are significantly associated with hypertension." (PMID 34828409, 2021). "Since the excessive generation of reactive oxygen species (ROS) seems to have a critical role in the pathogenesis of hypertension, the genetic variation of ALDH2 might be associated with the dysregulation of the ROS, which results in hypertension." (PMID 34828409, 2021). "Higher incidence rates of insensitivity to nitroglycerin treatment for angina, coronary spasm, myocardial infarction, hypertension, stroke and other oxidative-related neurodegenerative diseases have also been associated with the ALDH2*2 polymorphism in previous studies." (PMID 32932651, 2020). "Moreover, ALDH2 rs671 A allele is also associated with hypertension and cerebral amyloid angiopathy." (PMID 32107439, 2020). "In addition, the ALDH2 genetic variant rs2238152, which is in complete linkage disequilibrium with rs671 (ALDH2*2), was found to be associated with progression to hypertension in a prospective Chinese cohort." (PMID 32932651, 2020). "In addition, the Stanford Asia-Pacific Program for Hypertension and Insulin Resistance (SAPPHIRe) study showed that ALDH2 genetic variants were associated with progression to hypertension in a prospective Chinese cohort." (PMID 30857519, 2019). "Furthermore, serum ALDH2 levels can be influenced not only by the ALDH2 gene G487A polymorphism, but also by environmental factors, such as hypertension, obesity, diabetes mellitus and hyperlipidaemia." (PMID 29278292, 2018). "Within this study, we showed comparable causal effect estimates of alcohol intake on BP and hypertension risk in a sample of the Korean population, using both alcohol flushing and genetic variants associated with alcohol intake (including the ALDH2 rs671 polymorphism [G > A]) as separate IVs." (PMID 29323248, 2018).
Hypertension (continued). "In conclusion, this study supports a causal effect of alcohol intake on hypertension and indicated that alcohol flushing may be a valid proxy for the ALDH2 rs671 polymorphism, which influences alcohol intake in this Korean population." (PMID 29323248, 2018). "ALDH2 was previously shown to be associated with BP and hypertension The acyl-CoA dehydrogenase family member 10 gene (ACAD10) is located at 12q24.12 (NCBI Gene), is ubiquitously expressed (The Human Protein Atlas), and activates the β-oxidation of fatty acids in mitochondria (NCBI Gene)." (PMID 28562329, 2017). "The interaction between lifestyle and ALDH2 genetic polymorphism might affect hypertension incidence in adult Chinese Han population." (PMID 28894224, 2017). "In addition, Several previous studies have assessed SNPs in the ALDH2 gene for the association with the risk of diseases, such as coronary artery disease, diabetes, hypertension, lacunar infarcts." (PMID 29254215, 2017). "Our study was conducted to investigate whether ALDH2 genetic polymorphism and alcohol intake affect the onset of hypertension." (PMID 28894224, 2017). "Theoretically, decreased ALDH2 mutant enzyme activity may lead to an increase in reactive oxygen which predisposed to hypertension." (PMID 28894224, 2017). "Then ALDH2 mutation is tied with the increased prevalence of hypertension." (PMID 29254215, 2017). "Several studies confirmed that the ALDH2 rs671 polymorphism is associated with hypertension." (PMID 28894224, 2017). "The mutant ALDH2*2 gene was associated with an increased risk of hypertension in human, the blood pressure and ALDH2 enzymatic activity may be affected by gene and environment, such as life-style and ethnicity." (PMID 29254215, 2017). "As individuals with ALDH2∗1/∗1 are expected to consume more alcohol than those with the other genotypes, most part of the association of the ALDH2 polymorphism with hypertension might be due to difference in alcohol intake." (PMID 26185357, 2015). "Although the mechanism by which the ALDH2 *2 allele protects against hypertension in drinkers remains to be elucidated, the direct and indirect vasodilating actions of acetaldehyde may partly explain this effect." (PMID 26599441, 2015). "In addition, epidemiological studies revealed higher risks of MI, hypertension, osteoporosis and diabetes in humans carrying an inactivating mutation in ALDH2, especially in East Asian countries." (PMID 24040162, 2013). "Alcohol intake modified the genetic effect of ALDH2 variant on hypertension risk." (PMID 22839215, 2012). "However, previous cross-sectional or case–control studies had demonstrated significant association between ALDH2 variants and hypertension." (PMID 22839215, 2012). "In this study, we aimed to examine whether common ALDH2 genetic polymorphism predict development of hypertension in a prospective Chinese family cohort." (PMID 22839215, 2012). "We next examined whether there was interaction between the ALDH2 SNP and environmental factors on the risk of hypertension." (PMID 22839215, 2012). "Furthermore, the prevalent ALDH2 Glu504Lys polymorphism (ALDH2*2) in East Asian people, which exhibits reduced catalytic activity, was identified as an independent risk factor for decreased kidney function in Japanese patients with hypertension." (PMID 39226171, 2024). "Accordingly, the protective effects of ALDH2 against oxidative damage through acetaldehyde would be lost, resulting in increased risk of numerous oxidative stress-related diseases such as cancer, diabetes, inflammatory disorders and cardiovascular conditions such as hypertension and stroke." (PMID 35296751, 2022). "Accumulating evidence suggests that the ALDH2 rs671 polymorphism is associated with the risk of CAD in Asian population, and the mechanisms may relate to the effect of ALDH2 rs671 polymorphism on hypertension, dyslipidemia, and endothelial asymmetric dimethylarginine (ADMA) levels." (PMID 29960587, 2018).
Hypertension (continued). "Mitochondrial ALDH2 is responsible for the metabolism of toxic aldehydes.Individuals carrying inactive ALDH2 may have a lower risk of alcohol-induced high blood pressure than people with the wild-type enzyme, who can consume more alcohol without experiencing acetaldehydemia." (PMID 28472173, 2017). "Therefore, both lifestyle factors such as alcohol drinking and other genetic variations may have impacts on the susceptibility of ALDH2 genotypes to hypertension." (PMID 26491656, 2015). "For example, previous studies have reported an association between hypertension and ATP2B1 and ALDH2 gene variants." (PMID 39684400, 2024). "Our updated meta-analysis demonstrated that ALDH2 rs671 GG populations had significantly higher levels of BMI, blood pressure, FBG, TG, LDL-C and higher risk of hypertension than GA/AA populations." (PMID 38567307, 2024). "ALDH2 mutants have lower levels of BMI, providing a partial explanation for the correlation between ALDH2 polymorphism and T2DM and hypertension." (PMID 38567307, 2024). "In conclusion, SGR has an antihypertensive effect on L-NAME-induced hypertension, with ALDH2 as its hub target." (PMID 38783958, 2024). "The prevalence rates of diabetes mellitus, hypertension, and stroke, as well as salt intake restriction, were lower in ALDH2*1/*2 than in ALDH2*1/*1 carriers." (PMID 37164758, 2023). "It has been shown that ALDH2 rs671 polymorphism is strongly linked to an increased risk of various diseases (such as CAD, heart failure, hypertension, diabetes mellitus, stroke, and so on), some of which are predisposing factors to AF." (PMID 36426220, 2022). "In the present study, the association of ALDH2 rs671 and MTHFR rs1801133 polymorphisms with hypertension was analyzed among Hakka people in Southern China." (PMID 35346052, 2022). "After adjustment by multivariate analysis, ALDH2*2 (OR: 2.643; 95% CI, (1.286, 5.434); P = 0.008) and hypertension (OR: 2.012; 95% CI, (1.011, 4.001); P = 0.046) remained significant factors." (PMID 36426220, 2022). "Herein, the association between acetaldehyde dehydrogenase 2 (ALDH2) and methylenetetrahydrofolate reductase (MTHFR) gene polymorphisms and hypertension was analyzed among Hakka population in southern China." (PMID 35346052, 2022). "Studies have suggested that the ALDH2*2 allele is an important risk factor for ischemic stroke in Taiwanese and Korean men, as well as in Chinese women (OR = 2.207, 95% CI 1.416–3.439), since it increases dyslipidemia, hypertension, and diabetes, which may contribute to cerebral arteriosclerosis." (PMID 36258220, 2022). "The results of studies on the relationship between ALDH2, MTHFR gene polymorphisms and hypertension are inconsistent." (PMID 35346052, 2022). "According to the current data from this and other studies, the results on the relationship between ALDH2 and MTHFR gene polymorphisms and hypertension are inconsistent." (PMID 35346052, 2022). "Our study suggested that ALDH2 rs671 L-genotypes are protective factors for hypertension in Han Chinese." (PMID 28894224, 2017). "The minor allele of ALDH2 rs671 was associated with CAD, high LDL, and low HDL, while the major allele was associated with high blood pressure, and high FBG." (PMID 29016630, 2017). "Overall, our findings suggest a compensatory activation of cardiac ALDH2 and proteasome in order to maintain protein quality control during hypertension-induced compensatory cardiac remodeling." (PMID 25954323, 2015). "SGR may regulate neutrophil, regulatory T cell, and other cells’ infiltration by targeting ALDH2, thereby contributing to the treatment of hypertension." (PMID 38783958, 2024). "Therefore, this study aims to investigate the mechanism of SGR in treating hypertension by targeting ALDH2 using proteomics, bioinformatics, and experimental validation strategies." (PMID 38783958, 2024).
Hypertension (continued). "After adjusting age, sex, history of smoking and drinking, hypertension, and diabetes, ALDH2 rs671 A/A and MTHFR rs1801133 T/T genotypes may be independent risk factors for arteriosclerosis in multiple arteries." (PMID 37355582, 2023). "The present study focusing on circulating CD34-positive cells, platelets, HTLV-1, and SNPs in VEGF, BRAP, and ALDH2 has shown that active endothelial repair, which leads to the progression of structural atherosclerosis, partly indicates the prevention of hypertension." (PMID 37511963, 2023). "Previous studies showed that polymorphisms of the ALDH2 and MTHFR gene result in reduced enzyme activity may increase the risk of hypertension." (PMID 35346052, 2022). "In summary, ALDH2 rs671 G/A, A/A genotypes and MTHFR rs1801133 C/T, T/T genotypes may be risk factors for hypertension in this Chinese Hakka population." (PMID 35346052, 2022). "ALDH2 rs671 A allele decreased risk of hypertension in men, but not women in a Chinese population in Zhejiang Province, China." (PMID 35346052, 2022). "We hypothesized that polymorphisms of the ALDH2 and MTHFR gene that result in reduced enzyme activity may increase the risk of hypertension." (PMID 35346052, 2022). "Interestingly, in female AF patients, ALDH2*2 and hypertension were found to promote persistent AF events, but this effect was not seen in male AF patients." (PMID 36426220, 2022). "In this study, ALDH2 rs671 G/A, A/A genotypes and MTHFR rs1801133 C/T, T/T genotypes may be risk factors for hypertension in a Chinese Hakka population." (PMID 35346052, 2022). "The present study showed ALDH2 rs671 G/A, A/A genotypes and MTHFR rs1801133 C/T, T/T genotypes may be risk factors for hypertension in a Chinese Hakka population." (PMID 35346052, 2022). "ALDH2 activity is related to the occurrence and development of hypertension." (PMID 35346052, 2022). "However, the results of studies on the relationship between ALDH2, MTHFR gene polymorphisms and hypertension are inconsistent." (PMID 35346052, 2022). "A study has shown that ALDH2 rs671 A allele was a negative risk factor of essential hypertension in Mongolians from Inner Mongolia." (PMID 35346052, 2022). "Additionally, aldehyde dehydrogenase II (ALDH-2) polymorphisms have been associated with SUA levels and hypertension in genome wide association studies." (PMID 33498870, 2021). "The ALDH2 gene has a functional implication in the development of hypertension." (PMID 34828409, 2021). "Polymorphisms of ALDH2 rs671 are associated with clustering CRFs, especially hypertension and diabetes in males, but not in females." (PMID 33276716, 2020). "It had been postulated that gender factors do not affect ALDH2 rs671 polymorphism–related hypertension." (PMID 28894224, 2017). "Amamoto20 found that wild ALDH2 genotype correlates with the susceptibility of essential hypertension in Chinese men and ALDH2 deficiency does not affect women’s blood pressure." (PMID 28894224, 2017). "Subset analysis among the 182 patients with lone AF and 914 controls (control II) (<60 years of age and without hypertension), both ALDH2 and ADH1B SNPs were significantly associated with AF (P = 0.013, OR = 0.7; P = 0.0007, OR = 1.4, respectively)." (PMID 27927211, 2016). "In order to characterize the cardiac protein quality control profile during hypertension-induced compensated hypertrophy we evaluated E3 ubiquitin ligases Atrogin and MuRF-1, proteasomal α5/α7, β1, β5, and β7 subunits, and ALDH2 protein levels in heart homogenates from control, SHR, and SHRt." (PMID 25954323, 2015). "Previously, we reported that alcohol intake increases the risk of hypertension and elevates systolic and diastolic BP much more significantly in ALDH2*2 allele carriers than in non-carriers in a dose-dependent manner." (PMID 24028448, 2013). "We did not detect significant interaction between ALDH2 SNPs and other environmental factors including age, sex, smoking or physical activity on hypertension risk (data not shown)." (PMID 22839215, 2012).
Hypertension (continued). "The association was strongest in participants with heavy/moderate alcohol intake and was absent in participants who did not drink, indicating an interaction between ALDH2 genetic variation and alcohol consumption on hypertension risk." (PMID 22839215, 2012). "We examined whether the ALDH2 SNP genotypes predicted the development of hypertension in the prospective SAPPHIRe cohort." (PMID 22839215, 2012). "Notably, four loci (rs11899121 [chr2p24], rs7556898 [chr2q24.3], rs17249754 [ATP2B1], and rs1980854 [chr20p12.2]) were significantly associated with hypertension in the high-METS-IR group (T3), rs10857147 (FGF5) was significant in both T1 and T3, and rs671 (ALDH2) was significant only in T1." (PMID 39684400, 2024). "Besides, the most recent meta-analysis discussing ALDH2 and hypertension (Zheng et." (PMID 38567307, 2024). "In addition, several studies suggest that ALDH2 protects against oxidative stress and could influence the onset of hypertension." (PMID 36258220, 2022). "ALDH2 rs671 A/A genotype and A allele might increase the risk of hypertension, and ALDH2 rs671 polymorphism might be a risk factor of hypertension in non-drinking Han Chinese." (PMID 35346052, 2022). "Habitual drinkers, regardless of the presence of ALDH2 polymorphism, were generally more likely to be active smokers or prior smokers, more likely to have a history of hypertension, hyperlipidemia treatment, and a higher prevalence of CAD and CVD compared to non-drinkers (p < 0.05)." (PMID 34827557, 2021). "The risk associated with the rs2238152 T allele was strongest in heavy/moderate alcohol drinkers and was reduced in non-drinkers, indicating an interaction between ALDH2 genetic variants and alcohol intake on the risk of hypertension, which is also an important risk factor for AF." (PMID 32932651, 2020). "However, our subgroup analysis revealed that the ALDH2 polymorphism was a risk factor for hypertension even in nonhabitual drinkers." (PMID 26185357, 2015). "The risk associated with the rs2238152 T allele were strongest in heavy/moderate alcohol drinkers and was reduced in non-drinkers, indicating an interaction between ALDH2 genetic variants and alcohol intake on the risk of hypertension (P for interaction = 0.04)." (PMID 22839215, 2012). "ALDH2 can exert antioxidant effects by metabolizing 4-HNE, thereby inhibiting the occurrence and development of hypertension." (PMID 38783958, 2024). "Similarly genetic epidemiological studies focusing on genetic variants (rs671/rs1229984) within the aldehyde/alcohol dehydrogenase (ALDH2/ADH1B) gene demonstrated that individuals carrying the risk allele for alcohol consumption had a higher risk of hypertension and CVD compared to non-carriers." (PMID 35885821, 2022). "In addition, ALDH2 rs671 polymorphism might be no correlated with hypertension in aged patients from Jiangsu Province, China." (PMID 35346052, 2022). "Similarly, ALDH2 plays an important protective role at mitochondrial level in several human diseases (neurodegenerative diseases, stroke, cancer), including heart failure and cardiac dysfunction triggered by ischaemic injury, hypertension, alcohol and diabetes." (PMID 35712781, 2022). "Our data suggest that, during hypertension-induced compensated cardiac hypertrophy, the increased 4-HNE generation through lipid peroxidation is counteracted by elevated ALDH2 activity, the main enzyme responsible for removing intracellular 4-HNE." (PMID 25954323, 2015). "The proteomic response that contributes to the SHR phenotype and reduction of hypertension in Taichong-needled rats includes the modulation of seven proteins related to oxidative stress, including SOD, ALDH2, GSTM5, GLUD1, protein DJ-1, HSP90α, and α-ETF." (PMID 22984478, 2012). "Overall, habitual alcohol users were more likely to be men regardless of ALDH2 genotype and showed a higher prevalence of hypertension in ALDH2 Wt group." (PMID 37280327, 2023).